IGF1 (insulin like growth factor 1)
Diseases named in the same sentence as IGF1 in open-access papers (continued):
Sharing a sentence is not in itself a finding about the gene and the disease.
acromegaly (continued). "For patients who have not remitted after surgery and cannot be operated on, radiotherapy and/or drug therapy should be considered to achieve biochemical remission of GH/IGF-1 levels in patients with acromegaly as soon as possible." (PMID 33869029, 2021). "Many studies also demonstrated that both primary and secondary prolonged treatments with SAs are able to induce an enduring GH/IGF-1 reduction and a pituitary tumour volume decrease in most patients with acromegaly." (PMID 34018167, 2021). "Although their samples were within the clinical RR, the postoperative acromegaly group showed a significant increase in IGF-1 values vs. controls (155.2 ± 51.4 ng/mL, p = 0.01)." (PMID 33671326, 2021). "The tests for the diagnosis of acromegaly are measurement of both serum GH, and GH after oral glucose administration; serum insulin-like growth factor-1 (IGF-1)." (PMID 35262296, 2021). "Significant risk factors for colon neoplasia in acromegalic patients are still believed to be an adenoma on initial screening, as well as elevated serum concentrations of GH or IGF-1, i.e., uncontrolled acromegaly." (PMID 34208601, 2021). "Measurement of serum concentrations of insulin‐like growth factor (IGF)‐1 is used to diagnose acromegaly in cats." (PMID 33830548, 2021). "Acromegaly patients suffer from a higher incidence of vertebral fractures and accelerated bone turnover due to excessive GH and IGF-1 production." (PMID 34603213, 2021). "Acromegaly is a rare disease resulting from chronic exposure to high levels of growth hormone (GH) and its main mediator, insulin-like growth factor 1 (IGF-1)." (PMID 34081617, 2021). "In our previous publication, it has been shown that the IGF-1 acromegaly model is comparable to the IGF-1 acromegaly level." (PMID 33849304, 2021). "It is considered that high GH and IGF-1 levels can lead to cancer incidence increase in acromegaly patients due to mitogenic and antiapoptotic properties." (PMID 34530525, 2021). "In reference to acromegaly, criteria of cure in patients treated by GK includes mainly normalization of insulin-like growth factor 1 (IGF1) and/or GH levels (typically < 1μg/L)." (PMID 34638482, 2021). "Previous studies have suggested excess GH/IGF1 secretion in patients with acromegaly is protective for periodontal health." (PMID 33154456, 2020). "Long-acting SRLs have proven benefits in patients with acromegaly, reducing tumor volume (TV), decreasing GH and IGF-1 levels, and improving comorbidities." (PMID 31879842, 2020). "Presumably, in patients with acromegaly, the pathogenesis of goiter is related mainly to an increased level of insulin-like growth factor-1 (IGF-1), which binds to its specific receptor, expressed in thyrocytes." (PMID 32555993, 2020). "Patients with acromegaly exhibit a wide range of clinical symptoms due to the chronic influence of GH over-secretion and IGF-1 overproduction and tumor mass effects." (PMID 33335513, 2020). "The PK profiles of lanreotide autogel in Chinese patients with acromegaly demonstrated sufficient exposure to adequately maintain IGF-1 and GH suppression." (PMID 32366244, 2020). "Registration trials evaluating currently available injectable SRLs in patients with acromegaly were primarily open-label, single-arm studies that assessed treatment efficacy based on maintenance of IGF-1 and GH levels." (PMID 32882036, 2020). "In their study, only 17 out of 47 acromegaly patients had hypogonadism, while all acromegaly subjects in our study had hypogonadism, and moreover, their patients had lower GH and IGF1 levels as compared to our patients." (PMID 33154456, 2020). "Acromegaly patients, even those with IGF-1 values within the normal range receiving somatostatin receptor ligands (SRLs), often suffer from significant symptoms." (PMID 31808101, 2020). "Acromegaly treatment reverses some of the early stage morphological changes and improves cardiac function, especially when IGF-1 levels were normalized." (PMID 32458292, 2020).
acromegaly (continued). "Acromegaly is a rare endocrine disorder characterised by increased production of growth hormone (GH) and insulin-like growth factor 1 (IGF-1) due to a benign pituitary tumour." (PMID 32725444, 2020). "Lanreotide autogel was non-inferior to lanreotide 40 mg PR in Chinese patients with acromegaly in terms of IGF-1 SDS values." (PMID 32366244, 2020). "GH and IGF-1 excess exerts many actions on the cardiovascular (CV) system, and CV comorbidities and disease (CVD) risk factors are common, especially in active acromegaly, but often persist after adequate treatment in patients with controlled disease." (PMID 32458292, 2020). "Even when medical therapy successfully regulates production of GH and IGF-1 to within thresholds of normal, acromegaly symptoms can interfere with daily life, leisure, and work." (PMID 31808101, 2020). "The diagnosis of acromegaly was challenging due to the GH/IGF-1 discrepancy, which was surpassed by the use of a cut-off which was adjusted to the assay." (PMID 32079542, 2020). "Elevated levels of serum growth hormone (GH), combined with its product hormone insulin-like growth factor 1 (IGF-1), contribute to the systemic complications responsible for the increased mortality of acromegaly patients." (PMID 33193111, 2020). "Lanreotide autogel 120 mg at intervals of >4 weeks provided IGF-1 control in more than 90% of patients with acromegaly." (PMID 32725444, 2020). "In a recent series report, 31% of 157 treatment-naive patients with acromegaly had elevated IGF-1 and normal 24 hours mean plasma GH levels." (PMID 32079542, 2020). "The improvement of OSAS parameters is related to the decrease in IGF-1 levels; this represents another clinically relevant reason for stringently aiming towards normalization of IGF-1 in patients with acromegaly." (PMID 31612224, 2020). "Despite receiving a stable dose of SRL and regular visits with an acromegaly healthcare provider, US acromegaly patients in routine clinical practice, and even the subgroup with normal IGF-1, report significant burden of disease and treatment." (PMID 32736547, 2020). "CRP levels increase following IGF-1 lowering therapy, and controlled acromegaly patients display similar levels as healthy controls." (PMID 32458292, 2020). "We also observed a significant decrease in serum insulin-like growth factor-1 levels in 6 patients after acromegaly." (PMID 33019423, 2020). "For example, pegvisomant, a growth hormone receptor antagonist, is used for normalizing IGF-1 levels in acromegaly and teprotumumab, which antagonizes IGF-1R, is used to treat thyroid eye disease." (PMID 32492897, 2020). "In patients with suspected acromegaly, the diagnosis is confirmed with biochemical tests including random serum IGF-1, and GH level following a glucose load." (PMID 32843993, 2020). "Meanwhile, serum asprosin levels in patients with the acromegaly course ≥5 years, high IGF-1 SDS, and high GH-AUC were significantly decreased." (PMID 33414826, 2020). "Due to the popularization of biochemical measurements for GH and IGF-1 and easier online access to information on acromegaly, the disease duration has been reduced, as previously reported." (PMID 33335513, 2020). "The remission of acromegaly needs to meet the following two conditions at least 12 weeks after surgery: normalized levels of IGF1 and a random GH level of <1.0 μg/L or a nadir GH level of <0.4 μg/L following an oral glucose tolerance test (OGTT)." (PMID 33042013, 2020). "Acromegaly is a rare disease, resulting from excessive GH production and a consequent rise of IGF-1 levels." (PMID 32117056, 2020). "Elevated GH and IGF-1 levels commonly noted in patients with acromegaly and are also the basis of many differences between acromegaly and other diseases." (PMID 33414825, 2020). "Serum asprosin levels in acromegaly patients were negatively correlated with the course of acromegaly, IGF-1 SDS, nadir growth hormone value (GH-Nadir), and GH-AUC after OGTT." (PMID 33414826, 2020).
acromegaly (continued). "The time needed to achieve normalization of GH and IGF-1 levels has also been studied; it was achieved after a median follow-up of 4.9 months (range 1.2–117) in 53 patients with active acromegaly under treatment with lanreotide ATG." (PMID 32121432, 2020). "Achieving biochemical control (normalization of insulin-like growth factor-1 [IGF-1] and growth hormone [GH]) is a key goal in acromegaly management." (PMID 31741320, 2020). "Acromegaly is a disease characterized by the hypersecretion of growth hormone (GH)/insulin-like growth hormone-1 (IGF-1), typically as a result of a benign pituitary adenoma." (PMID 31879842, 2020). "Biochemical control status (controlled vs. uncontrolled) is defined according to the patient’s levels of IGF-1 and GH, which are known to fluctuate over time for reasons both related and unrelated to acromegaly." (PMID 31741320, 2020). "Overall, when assessing patients with acromegaly, concomitant and parallel changes in serum sKlotho and IGF-1 were observed over time in each patient, and levels of sKlotho and IGF-1 appeared to be similarly dependent on GH." (PMID 32333268, 2020). "The results obtained for GH and IGF-1 levels at week 12 resonate with established thresholds for disease control in acromegaly." (PMID 31879842, 2020). "Normally occurring IGF-1 fluctuations in patients with acromegaly should be considered when evaluating response to therapy." (PMID 32882036, 2020). "An Italian multicenter retrospective study also demonstrated that pre-treatment IGF-1 levels are predictors for both morbidity and mortality in patients with acromegaly." (PMID 31879842, 2020). "In acromegaly, excessive GH/IGF-1 leads to periosteal bone formation, growth of synovial tissue, cartilage and leading to hypertrophic arthropathy associated with pain and deformity, as also seen in pachydermoperiostosis." (PMID 31916215, 2020). "At the same time, serum asprosin levels in patients with the acromegaly course ≥5 years, high IGF-1 SDS group, and high GH-AUC were significantly decreased." (PMID 33414826, 2020). "Up to 99% of patients with acromegaly harbor a pituitary somatotroph adenoma, leading to growth hormone (GH) and Insulin-like growth factor 1 (IGF-I) hypersecretion, resulting in multi-system implications." (PMID 32849283, 2020). "The role of IGF-1 in increased thyroid gland volume in patients with acromegaly has been confirmed by numerous studies." (PMID 32555993, 2020). "Acromegaly is a rare disease, secondary to the chronic hypersecretion of growth hormone and insulin-like growth factor-1, with characteristic metabolic and somatic effects." (PMID 32079542, 2020). "The presence of coronary microvascular dysfunction correlated with IGF-1 circulating concentrations and was partially reversed by acromegaly treatment." (PMID 32458292, 2020). "Transition to acromegaly was observed in 2 of 17 cases (two female patients developed progression with elevated IGF-1 levels during the follow-up period)." (PMID 30020466, 2019). "In contrast, due to its relatively stable levels and long half-life IGF-1 can be used for acromegaly screening." (PMID 31939489, 2019). "Acromegaly is characterized by glomerular hyperfiltration, and the urinary albumin level is high, suggesting the influence of GH and IGF-1 levels." (PMID 31540583, 2019). "Acromegaly is a multi-system disease characterized by overproduction of growth hormone (GH) and an accompanying increase in insulin-like growth factor-1 (IGF-1) levels, usually due to a GH-secreting pituitary tumor (predominantly macroadenomas)." (PMID 31338660, 2019). "In acromegaly, GH was correlated with CBTneck (r = 0.31, p = 0.020), whereas IGF‐1 was correlated with CBTcalcar (r = 0.39, p = 0.003) at baseline." (PMID 31844828, 2019). "Acromegaly diagnosis is based on the assessment of clinical manifestations, measurement of GH and IGF-1 levels, and pituitary magnetic resonance imaging (MRI)." (PMID 31338660, 2019).
acromegaly (continued). "Our observation that the frequency of certain manifestations differed between men and women accords with reports of differences in GH and IGF-1 levels and subsequent acromegaly diagnosis in men and women." (PMID 30269264, 2019). "A retrospective study investigated the efficacy of this combination therapy, and found that PEGV in combination with cabergoline normalized IGF-1 levels in 4 out of 14 acromegaly patients (28%) and decreased IGF-1 levels in 9 out of 14 patients (64%)." (PMID 31939490, 2019). "In contrast to PDP, acromegaly presents clinically with larger bones in the face, skull and limbs, jaw prognathism, along with elevated insulin-like growth factor-1 levels and positive oral glucose tolerance test." (PMID 30786934, 2019). "Corresponding to disease activity, the patients with acromegaly had higher GH and IGF‐1 at baseline compared with NFPA patients." (PMID 31844828, 2019). "This indicates that weight, IGF‐1, and GH differentially affect the femoral sites in active acromegaly, possibly related to different mechanical demands." (PMID 31844828, 2019). "The desired treatment approach in acromegaly patients should take all the individual traits of the disease into consideration, such as: GH and IGF-1 levels, tumour size, acromegaly symptoms, comorbidities, costs, QoL and patient preferences." (PMID 31939490, 2019). "The development of thyroid diseases in patients with acromegaly is correlated to the excessive secretion of IGF-1 and growth hormones." (PMID 31477080, 2019). "Treatment of acromegaly aims to normalize GH and IGF-1 levels, which reestablishes a normal life expectancy." (PMID 31412614, 2019). "Acromegaly is a rare disease, characterized by an excessive secretion of growth hormone (GH), and consequently the insulin like growth factor 1 (IGF-1)." (PMID 31616375, 2019). "We found that BMD in patients with acromegaly was elevated, and this change was likely to be the result of long-term chronic effects of high levels of GH and IGF-1." (PMID 31781204, 2019). "Acromegaly is a rare disease characterized by the increased release of growth hormone (GH) and insulin-like growth factor-1 (IGF-1)." (PMID 31406221, 2019). "Acromegaly results from persistent excess growth hormone (GH), which through the GH receptor stimulates the synthesis of circulating insulin-like growth factor-1 (IGF-1) mainly in the liver." (PMID 31766255, 2019). "Treatment options for acromegaly include surgery, medical therapy, and radiotherapy, which aim to control clinical signs and symptoms, normalize GH/IGF-1 excess, and reduce or remove the tumor mass." (PMID 30269264, 2019). "The aim of this review is to summarize the studies available on the effects of excess GH and IGF-1 on the endothelium, considering both basic and experimental research models, in particular in the context of acromegaly." (PMID 31396153, 2019). "In our study, in addition to previous literature data, there was an increase in LS value obtained by elastography examination in patients with acromegaly, which was closely related to IGF-1, SBP, and GGT levels." (PMID 30653179, 2019). "The current consensus for cure and remission of acromegaly is based upon biochemical control e.g., age-adjusted normal range of IGF-1 and GH < 1.0 μg/L (random GH measurement)." (PMID 31338660, 2019). "SSAs were first used in the treatment of acromegaly and pituitary adenomas through the reduction of growth hormone (GH) and insulin-like growth factor-1 (IGF-1) circulating levels." (PMID 31273555, 2019). "For the diagnosis of acromegaly, GH levels during oral glucose tolerance test and random IGF-1 levels should be measured." (PMID 31406221, 2019). "In our study, we revealed a negative correlation between fasting GH and FokI ff genotype in all acromegaly groups and with IGF-1 levels in the cured disease group." (PMID 31616375, 2019).
acromegaly (continued). "High levels of IGF-1 promote cell proliferation and inhibit apoptosis, and are responsible for most of the clinical manifestations of acromegaly." (PMID 31766255, 2019). "Growth hormone-producing adenomas (GHomas) can lead to acromegaly and the increased secretion of insulin-like growth factor 1 (IGF-1)." (PMID 31508369, 2019). "As there was a suspicion of acromegaly, we investigated the levels of insulin-like growth factor-1 and performed an oral glucose tolerance test; the results of both of these tests were normal." (PMID 30786934, 2019). "Treatment goals for management of acromegaly include reduction of tumor size and prevention of further tumor growth, and control of excessive GH secretion and IGF-1 levels." (PMID 31338660, 2019). "We report a case of a patient with FSGS in whom the urinary protein level improved as the concentration of GH/IGF-1 decreased after surgical treatment for acromegaly." (PMID 31540583, 2019). "Quantitative analysis of facial changes is necessary for the accurate identification of the acromegaly-specific face, which also assists in early facial recognition and in shortening the exposure duration to excessive GH and IGF-1." (PMID 30555420, 2018). "The aim of this review is to summarize the methods that are being applied to measure and report GH and IGF-1 in studies that evaluated medical treatment efficacy in acromegaly patients in peer-reviewed journals, published between 2012 and 2017." (PMID 29605877, 2018). "Acromegaly is a rare disease due to chronic GH excess and to the consequent increase in IGF-1 levels." (PMID 30034367, 2018). "The important role of the GH/IGF1 system in the growth of these organs is supported by their disproportionate overgrowth in conditions of GH/IGF1 excess, as in GH-overexpressing transgenic mice and in patients with acromegaly." (PMID 29678421, 2018). "Trans-sphenoidal surgery is the treatment of choice in acromegaly, because it can provide prompt reduction of GH and IGF-1 levels, thereby improving morbidity and mortality." (PMID 29563895, 2018). "The GH and IGF-1 levels were significantly increased in the patients with acromegaly and in the subgroup comparisons." (PMID 29531529, 2018). "Acromegaly patients, in contrast to diabetic non-acromegaly ones, generally have a low amount of visceral fat and insulin resistance is mainly related to GH/IGF-1 excess." (PMID 30034367, 2018). "Cabergoline can be attempted as a first-line medical therapy in patients with acromegaly and mildly elevated levels of IGF1 of <2.5 times the upper limit of normal (DR)." (PMID 30050156, 2018). "Our study is the first to show that both the random GH and nadir GH levels, together with IGF-1, are positively correlated with thyroid volume in acromegaly." (PMID 29593792, 2018). "Surgery to remove the pituitary adenoma is generally the first-line therapy for acromegaly with the goal of normalizing the GH and IGF-1 levels." (PMID 30619084, 2018). "The aim of this review was to investigate the current methods that are being applied to measure and report growth hormone (GH) and insulin-like growth factor-1 (IGF-1) as markers for drug effectiveness in clinical acromegaly research." (PMID 29605877, 2018). "For the acromegaly patients, the average disease duration was 72 months, and the average GH level, GH nadir level and IGF-1 level were 30.8, 22.8, and 875.1 ng/ml, respectively." (PMID 30555420, 2018). "Both the GH and IGF-1 plasma concentrations are typically increased in active acromegaly and will decrease during effective treatment." (PMID 29605877, 2018). "Recently, pasireotide was approved for acromegaly and showed more efficacy in controlling GH and IGF-1 levels." (PMID 29853879, 2018). "High levels of growth hormone (GH) and insulin-like growth factor 1 (IGF-1) in acromegaly patients, which are mostly due to a GH-secreting pituitary adenoma, contribute to tissue proliferation and hypertrophy throughout the body." (PMID 30555420, 2018).